LRP6 (LDL receptor related protein 6)
Diseases named in the same sentence as LRP6 in open-access papers (continued):
Sharing a sentence is not in itself a finding about the gene and the disease.
breast cancer (continued). "In breast cancer cells, gigantol treatment significantly decreased the levels of phosphorylated LRP6, total LRP6 and cytosolic β-catenin, resulting in a decrease in the expression of Wnt target genes Axin2 and Survivin." (PMID 29444668, 2018). "For example, rottlerin suppressed the expression of LRP6 (low density lipoprotein receptor-related protein-6) and inhibited Wnt/β-catenin and mTORC1 signaling pathway in prostate and breast cancer cells." (PMID 28977931, 2017). "In the breast cancer, LRP6 is upregulated in the patients’ tissues and tumor cell lines, promoting tumor migration and invasion via Wnt/β-catenin signaling pathway." (PMID 29108281, 2017). "Recent studies have reveal an important role of LRP6 in contributing to tumor progression in breast cancer, hepatocellular carcinoma and colorectal cancer, but the exact molecular mechanism is still elusive." (PMID 29312635, 2017). "For instance, rottlerin induced LRP6 degradation and inhibited mTORC1 and Wnt/β-catenin signaling in breast cancer cells." (PMID 27582552, 2016). "Some have reported that niclosamide suppresses Wnt/β-catenin signalling via inducing lipoprotein receptor-related protein-6 (LRP6) degradation in prostate and breast cancer cells." (PMID 27652012, 2016). "They observed suppression of LRP6-expression in prostate and breast cancer cells after Sal-treatment." (PMID 27855654, 2016). "The tumor suppressive gene retinoic acid receptor responder 3(RARRES3) has been proved to inhibit cancer stem cell properties in breast cancer via targeting and modulating the acylation status of Wnt ligands and the co-receptor LRP6." (PMID 26337084, 2015). "Accumulating evidence indicates that Wnt co-receptor LRP6 play a critical role in the Wnt/β-catenin signaling activation in human prostate and breast cancer cells and is important in the development and progression of these two types of cancer." (PMID 23469146, 2013). "Using MMTV-LRP6 mice model, they further confirmed that LRP6 activated Wnt signaling and contributed to breast cancer tumorigenesis in vivo." (PMID 22570728, 2012). "Our results support the concept that LRP6 is a promising therapeutic target for breast cancer including TNBC." (PMID 22195040, 2011). "Our data from profiling of Wnt related genes show upregulation of several Wnt signaling pathway regulators in Rad6B overexpressing breast cancer cells, which are downregulated either by mutant LRP6 or Rad6B silencing." (PMID 21767405, 2011). "Taken together that similar outcomes on β-catenin activity, EMT suppression, or breast cancer progression are achieved by inhibiting LRP6 or Rad6B, illustrate the cooperation between the canonical Wnt signaling pathway and Rad6B in β-catenin activation." (PMID 21767405, 2011). "We looked at the expression pattern of Lrp6 in two published transcriptome profiles of breast cancer." (PMID 19503830, 2009). "Moreover, our results showed that IVM also inhibited Snail and LRP6 in ER-positive wild-type breast cancer cells, although the effect was less pronounced compared to hormone-resistant cells." (PMID 40569965, 2025). "In breast cancer cell models, bardoxolone methyl treatment led to significant depletion of phosphorylated LRP6 and phosphorylated Disheveled 2 (DVL2), alongside suppression of cytoplasmic β-catenin activation, resulting in the downregulation of Wnt target genes and cancer stem cell (CSC) markers." (PMID 40732256, 2025). "This evidence supports the potential of LRP6 as a therapeutic target for breast cancer." (PMID 40569965, 2025). "Furthermore, CGA can suppress epithelial–mesenchymal transition and invasion in breast cancer by downregulating the expression of LRP6, a component of the Wnt/β-catenin signaling pathway." (PMID 38398512, 2024). "Importantly, LRP6 is upregulated in around 60% of human malignant colorectal tissues and breast cancers, especially in the subset of triple-negative tumors." (PMID 36645301, 2023).
breast cancer (continued). "Moreover, overexpression of LRP6 has been shown in breast cancer and its inhibition reduced breast cancer growth." (PMID 35052459, 2022). "On the other hand, it is well established that LRP6 regulates breast cancer." (PMID 35865469, 2022). "The role of LRP6 in breast cancer tumorigenesis is highly dependent on Wnt/β-catenin signaling." (PMID 34589484, 2021). "Moreover, the tumor metastasis suppressor N-myc downstream regulated gene-1 (NDRG1) repressed Wnt/β-catenin signaling through interacting with LRP6, resulting in suppression of metastatic phenotypes of mammary tumor cells." (PMID 34615853, 2021). "Consequently, our results indicate that the functional interaction between USP19 and LRP6 is key for the regulatory effect that USP19 exerts on the modulation of breast cancer cell migration and invasion." (PMID 33714979, 2021). "We observed the downregulation of the Wnt pathway ligand Wnt-3A and the Wnt-dependent transcription factor TCF7L1 in Sdc-1-depleted MCF-7 cells, which is in accordance with our previous observation of a downregulation of the Wnt-coreceptor LRP6 in Sdc-1-depleted breast cancer cells." (PMID 34070901, 2021). "Taken together, these results indicate that TMEM97 could promote the LRP6-mediated Wnt signaling pathway via regulating LRP6 phosphorylation in breast cancer cells." (PMID 34615853, 2021). "In addition, niclosamide decreased the level of CSCs by reducing the expression of LRP6 and β-catenin in basal-like breast cancer." (PMID 33276800, 2020). "Moreover, low LRP6 expression worsened already poor prognosis of patients with breast cancer and high CXCR4 levels." (PMID 33096815, 2020). "Moreover, niclosamide, a teniacide of the antihelminthic family, induces LRP6 degradation in breast cancer cell lines, resulting in increased cell apoptosis and decreased cell proliferation." (PMID 31412666, 2019). "Multiple small molecule LRP6 inhibitors, such as salinomycin, prodigiosin, niclosamide, silibinin and rottlerin, have been identified to exert anticancer activity in breast cancer cells." (PMID 29444668, 2018). "Several studies have shown that LRP6 is up-regulated in human breast cancer cells." (PMID 29444668, 2018). "Furthermore, we observed a significant decrease in cytosolic β-catenin after gigantol treatment, indicating that gigantol inhibits Wnt/β-catenin signaling in breast cancer cells by suppressing LRP6 expression." (PMID 29444668, 2018). "We analyzed expression of the WNT coreceptors LRP5 and LRP6 in human breast cancer samples." (PMID 29854300, 2018). "As shown here, CDK3 exhibited a potent inhibitory effect on Wnt signaling in breast cancer cells through regulating the phosphorylation level of LRP6, the expression of Axin1 and Dvl2, leading to the inhibition of β-catenin, and this process is possibly due to decreased expression of Wnt3a." (PMID 29156693, 2017). "In addition, in LRP6-mice model, LRP6 promoted Wnt signaling and accelerated tumorigenesis in breast cancer." (PMID 27806330, 2016). "A potential contribution of this potential feedback loop to regulation of LRP6 expression in breast cancer cells is currently unknown." (PMID 25090092, 2014). "We did not observe statistically significant association with the risk of developing breast cancer for the SNPs in APC, DKK4 and LRP6 as well as some of the SNPs in β-catenin (rs13072632), AXIN2 (rs4791171, rs11079571 and rs3923086) and SFRP3 (rs288326) in the overall study population." (PMID 23516639, 2013). "In this study, we utilized MDA-MB-231 and HCC38 cells to evaluate the canonical WNT-signaling pathway in triple negative (TN) breast cancers since this pathway is activated evaluated by LRP6 expression, suggesting that the WNT-signaling pathway is activated in these cell lines." (PMID 22984505, 2012).
breast cancer (continued). "Two very recent reports by Bu's group showed that LRP6 was overexpressed in a subpopulation of human breast cancers and, more importantly, demonstrated that activation of the Wnt signaling by overexpressing LRP6 alone was enough to induce breast cancer formation." (PMID 22570728, 2012). "Our data indicate that niclosamide is a unique small molecule Wnt/β-catenin signaling inhibitor targeting the Wnt co-receptor LRP6 on the cell surface, and that niclosamide has a potential to be developed a novel chemopreventive or therapeutic agent for human prostate and breast cancer." (PMID 22195040, 2011). "Moreover, salinomycin, a breast cancer stem cell killer, was recently demonstrated to be an inhibitor of Wnt/β-catenin signaling by inducing LRP6 degradation." (PMID 22195040, 2011). "Consistent with this, our present data show that inhibition of LRP6 signaling in R6B-Zshigh breast cancer cells induces a reduction in Rad6B promoter activity as evidenced by decrease in Rad6B promoter-mediated ZsGreen and luciferase reporter expressions and Rad6B gene expression." (PMID 21767405, 2011). "However, our results suggest that Lrp5 plays a pivotal role over Lrp6 in transmitting oncogenic Wnt signals in the MMTV-Wnt1 mammary tumor model." (PMID 19503830, 2009). "Treatment with apigenin and chrysin reduced liver cancer HepG2 and breast cancer MDA-MB-231 cell viability as well as induced apoptosis via down-regulation of S-phase kinase-associated protein-2 (Skp2) and low-density lipoprotein receptor-related protein 6 (LRP6) expression." (PMID 36144783, 2022). "In addition to Fz7, targeting Wnt ligands, Dkk1 or Lrp6 at the membrane may offer promising treatment options against breast cancer." (PMID 33585487, 2021). "Hence, therapeutic interventions targeting LRP5 and/or LRP6 could be useful in treating some types of breast cancer, particularly the basal-like class for which few, if any, effective treatments exist." (PMID 19503830, 2009). "On the other hand, niclosamide suppressed the LRP6 expression in TNBC MDA-MB-231 cells and ER-positive breast cancer T-47D cells and inhibited breast cancer cell proliferation with IC50 values less than 1 mM." (PMID 37259421, 2023). "HT decreased the expression levels of the WNT co-receptors LRP6, β-catenin, SNAIL, and SLUG and increased E-cadherin expression in a breast cancer cell line." (PMID 36835384, 2023). "Sox9 has been shown to mediate the Wnt/β-catenin activation through the regulation of LRP6 and TCF4 expression in breast cancer." (PMID 34615853, 2021). "In breast cancer tissue, high expression of the Sry-related HMG box 9 protein (SOX9) activates Wnt/β-catenin signaling by inducing LRP6 expression." (PMID 34589484, 2021). "In breast cancer cells, knockout of TMEM97 attenuated the Wnt/β-catenin signaling cascade via regulating LRP6 phosphorylation, leading to a decrease in the expression of Wnt target genes AXIN2, LEF1, and survivin." (PMID 34615853, 2021). "This phenomenon was particularly pronounced in breast cancer patient-derived xenograft (PDX) models, in which alterations of LRP5 were observed in more than 50% of cases, versus less than 7% of cases for LRP6." (PMID 29854300, 2018). "In breast cancer MDA-MB-231 and MDA-MB-468 cells, treatment with gigantol reduced the level of phosphorylated LRP6, total LRP6 and cytosolic β-catenin in a dose-dependent manner, resulting in a decrease in the expression of Wnt target genes Axin2 and Survivin." (PMID 29444668, 2018). "For example, Niclosamide that blocked Wnt co-receptor LRP6 suppressed the growth of Wnt-driven MDA-MB-231 and T-47D breast cancer cells." (PMID 29433490, 2018). "Low expression of LRP6 in ER+ve tumours was predictive of early recurrence, whilst low levels of LRP5 was predictive of early recurrence in ER-ve breast cancer." (PMID 23861811, 2013).
breast cancer (continued). "In the present study, we demonstrated that niclosamide suppressed LRP6 expression in TNBC MDA-MB-231 cells and ER-positive breast cancer T-47D cells, and inhibited breast cancer cell proliferation with IC50 values less than 1 μM." (PMID 22195040, 2011). "Breast cancer subpopulations selected for high Rad6B produce tumors with the EMT phenotype, which is suppressed by blocking LRP6 function." (PMID 21767405, 2011). "Furthermore, in the breast cancer cell line MCF-7, an shRNA-based knockdown of LRP6 resulted in reduced tumor growth." (PMID 38761292, 2024). "Previous studies have reported a pro-proliferative role of LRP6 also in non-neuronal cell types, i.e., vascular smooth muscle cell, breast cancer cells, and hepatocellular carcinoma cells." (PMID 37091972, 2023). "As a single-pass transmembrane receptor, LRP6 interacts with the frizzled (FZD) family and activates the Wnt/β-catenin signaling pathway, which has been demonstrated in many cancers, including breast cancer, prostate cancer, hepatocellular carcinoma, and retinoblastoma 40,42." (PMID 36035366, 2022). "Injection of Lrp6-silenced EO771 cells did not alter mammary tumors, and Lrp6-silenced osteocyte-derived CM did not suppress the antitumor action of osteocytes." (PMID 34230453, 2021). "The mushroom Ganoderma lucidum used in traditional Chinese medicine blocked Wnt signaling through inhibiting the phosphorylation of LRP6 in human (MDA-MB-231) and mouse (4T1) breast cancer cell lines, also suppressing Wnt3a-activated expression of Axin2, a Wnt target gene." (PMID 32131438, 2020). "As observed in breast cancer cells, silibinin, rottlerin, salinomycin and niclosamide were demonstrated to inhibit WNT/β-catenin activity and pancreatic cancer cell growth by suppressing LRP6 expression or phosphorylation." (PMID 31412666, 2019). "Besides Salinomycin, Niclosamide was also reported to suppress LRP6 expression in TNBC MDA-MB-231 cells and ER-positive breast cancer T-47D cells where it inhibited breast cancer cell proliferation." (PMID 31031810, 2019). "We also examined the expression of these genes in a separate cohort of 698 luminal (ER/PR+) breast cancers using the TCGA dataset, where PIK3CA-mutant cancers displayed significantly higher expression of eight Wnt genes (LEF1, TCF7L1, TCF7L2, CTNNB1, LRP6, SFRP2, WNT5A, and MSX2)." (PMID 34035258, 2021). "Deletion of Lrp5 in tumor cells reduced mammary tumor growth, but deletion of Lrp6 did not." (PMID 34230453, 2021). "Interestingly, expression of LRP6, but not LRP5, has been shown to define a new class of breast cancer subtypes, as LRP6 is overexpressed in 20–36% of breast carcinomas." (PMID 31412666, 2019). "Given the stronger expression of the LRP5 and LRP6 coreceptors in TNBC than in other breast cancer subtypes, we then investigated the effects of knocking down LRP5 or LRP6 expression on cell viability in HCC38 and MDA-MB-468 TNBC cells, which have high levels of both LRP5 and LRP6." (PMID 29854300, 2018). "Indeed, kallistatin could bind to the Wnt co-receptor low-density lipoprotein receptor-related protein 6 (LRP6), thus blocking Wnt/b-catenin signaling as well as Wnt-mediated growth and migration in MDA-MB-231 breast cancer cells." (PMID 27980455, 2016). "In an orthotopic breast cancer mouse model in which metastatic 4T1 cells and non-metastatic 168FARN cells were injected, a treatment using the LRP6 ectodomain (LRP6N) resulted in reduction of metastasis, suggesting that LRP6 might be a suitable target for treating metastatic cancer." (PMID 38761292, 2024). "Furthermore, treatment of ER− breast cancer cells with pictilisib, a strong PI3Kα/δ and modest PI3Kβ/γ inhibitor, increased mRNA expression of Wnt ligands including WNT2B, WNT3, WNT5B and WNT10A, as well as phosphorylation of LRP6 and β-catenin nuclear translocation." (PMID 37471270, 2023).
breast cancer (continued). "Expression of Wnt coreceptors LRP6, but not LRP5, was found to be upregulated in a subset of human breast carcinomas, and downregulation of LRP6 was sufficient to inhibit breast carcinogenesis." (PMID 21767405, 2011). "We found that, compared to several other breast cancer cell lines, HCC1187 cells express a relatively high level of endogenous LRP6 (data not shown)." (PMID 20543981, 2010). "LRP6, but not LRP5, is frequently up-regulated in human breast carcinomas." (PMID 33488948, 2020).
hepatocellular carcinoma (27 papers, 2014 to 2025). A malignant tumor that arises from hepatocytes. "HSPA5 (GRP78) activates the Wnt/HOXB9 pathway to promote invasion and metastasis of hepatocellular carcinoma by chaperoning LRP6." (PMID 34918006, 2022). "In contrast, our data from HCT116 cells suggest that cyclin Y is uncoupled from LRP6 phosphorylation and Wnt signaling in intestinal epithelia, a phenomenon that has also been observed in hepatocellular carcinoma cells." (PMID 34571979, 2021). "A total of 45% of human hepatocellular carcinoma cells have overexpressed LRP6 and as a result, increased β-catenin levels, suggesting LRP6 as tumor-promoting." (PMID 31382613, 2019). "Then, we found the increased expression of LRP6 in oxaliplatin-resistant hepatocellular carcinoma with enhanced stemness." (PMID 28870205, 2017). "The involvement of miR-126 in the regulation of angiogenesis was shown also in hepatocellular carcinoma, where it acts as tumour suppressor by targeting LRP6 and PIK3R232." (PMID 28600498, 2017). "LRP6 is found to be targeted and suppressed by miR-126-3p leading to inhibition of tumor metastasis and angiogenesis of hepatocellular carcinoma." (PMID 25491321, 2014). "Likewise, LRP6 was found in hepatocellular carcinoma (HCC) whereby oxaliplatin-pretreated hepatocellular carcinoma showed the improvement of its stemness and increased expression of LRP6 and connective tissue development factor (CCN2)." (PMID 31031810, 2019). "GRP78 promotes malignant phenotype of hepatocellular carcinoma by activating the Wnt/HOXB9 signaling pathway and chaperoning LRP6." (PMID 35535309, 2022). "In hepatocellular carcinoma (HCC) cells, CR-1 binds and stabilizes DVL3, helped by the concomitant binding of the Frizzled receptor FZD7 and the transmembrane lipoprotein LRP6, resulting in a more sustained signal from the Wnt/β-catenin axis." (PMID 34360603, 2021). "By cDNA microarrays, we also found oxaliplatin-pretreated hepatocellular carcinoma exhibited the enhanced stemness and increased expression of CCN2 and LRP6." (PMID 28870205, 2017). "It was shown that depletion of GBA in hepatocellular carcinoma cell lines shifts these cells toward EMT, and it was shown that this effect was mediated in part by activation of the Wnt pathway via increased phosphorylation of LRP6." (PMID 37508550, 2023). "Furthermore, miRNA-126-3p reduces LRP6 and PIK3R2,59, which decreases angiogenesis in hepatocellular carcinoma (HCC)." (PMID 36765409, 2023). "In human hepatocellular carcinoma (HCC) cells, PEDF silencing increased activated LRP6 and β-catenin, while the 34-mer PEDF peptide decreased LRP6 activation and β-catenin signalling, reducing Wnt target genes." (PMID 40649783, 2025). "Similarly, downregulated miR-126-3p also fails to suppress tumor metastasis and angiogenesis of hepatocellular carcinoma by its reduced ability to repress LRP6 and PIK3R2 expression." (PMID 38256049, 2024). "MiR-126-3p was reported to suppress tumor metastasis and angiogenesis of hepatocellular carcinomas by targeting LRP6 and PIK3R2, and its restoration may be a promising strategy for HCC therapy." (PMID 29685146, 2018). "Although this was not investigated, there is strong evidence that LRP6 can be cross-activated by several RTKs, suggesting the possibility that the changes observed in GBA-depleted hepatocellular carcinoma-derived cells may also be due in part by alterations in RTK activity." (PMID 37508550, 2023).